SMN2 (survival of motor neuron 2, centromeric)
Diseases named in the same sentence as SMN2 in open-access papers (continued):
Sharing a sentence is not in itself a finding about the gene and the disease.
spinal muscular atrophy (continued). "In SMA patients, the SMN2 gene is the only source of SMN protein, and the number of its copies correlates with disease severity, which makes SMN2 the main modifier of spinal muscular atrophy." (PMID 36292797, 2022). "Spinraza is an ASO designed to increase expression of a stable form of survival motor neuron 2 (SMN2) protein and act as a therapy for spinal muscular atrophy (SMA)." (PMID 35289725, 2022). "Spinal muscular atrophy (SMA) results from the absence or mutation of SMN1, plus the inability of SMN2 to compensate for the loss of SMN1 due to exon seven jumping." (PMID 34630514, 2021). "The use of appropriate ASOs to treat spinal muscular atrophy allows exon 7 to be incorporated into the transcript of the SMN2 gene." (PMID 34573328, 2021). "In patients suffering from spinal muscular atrophy, the loss of SMN cannot be compensated by the homologous SMN2 gene, as it only produces low levels of functional SMN due to substantial exon 7 skipping." (PMID 34068052, 2021). "Spinal muscular atrophy (SMA) is caused by homozygous survival of motor neurons 1 (SMN1) gene deletion, leaving a duplicate gene, SMN2, as the sole source of SMN protein." (PMID 34638572, 2021). "Clinically effective oligonucleotide reagents targeting splicing events have reached the bedside for other disorders, notably for increasing specific exon inclusion in SMN2 to treat spinal muscular atrophy." (PMID 32915137, 2020). "Similar results are reported that the LNA/DNA mixmer compounds have better efficacies than all-LNA ASO with an equivalent sequence for SMN2 exon inclusion in human spinal muscular atrophy patient fibroblasts (PMC5473822)." (PMID 32572084, 2020). "For example, the ASO drug Nusinersen (Spinraza) corrects aberrant splicing of SMN2 and is an effective approved treatment for spinal muscular atrophy." (PMID 32481522, 2020). "Deletions encompassing exon 7 in SMN1 are the most frequent molecular cause of spinal muscular atrophy (SMA), while the number of SMN2 copies has been associated with severity and onset time of SMA24–26." (PMID 32944285, 2020). "A prime example for the therapeutic potential is the steric hindrance of an intronic SMN2 silencer element using an antisense oligonucleotide that boosts the inclusion of Exon 7 in SMN2 mRNA and effectively treats infantile-onset spinal muscular atrophy." (PMID 32225107, 2020). "Modification of SMN2 exon 7 (E7) splicing is a validated therapeutic strategy against spinal muscular atrophy (SMA)." (PMID 29795225, 2018). "We correlate chromosome 5 haplotypes and SMN2 copy number with disease expression in 42 Mennonite and 14 Amish patients with spinal muscular atrophy (SMA)." (PMID 30188899, 2018). "Beyond HD, correction of splicing deficits and consequent increases in the level of SMN2 in mouse models of spinal muscular atrophy improves hepatic phenotypes and greatly extends survival compared to treatments limited to the CNS." (PMID 28453524, 2017). "Nusinersen targeting intron 7 within Survival of Motor Neuron 2 (SMN2) restored splicing and facilitated production of full-length SMN2 in spinal muscular atrophy (SMA)." (PMID 29220444, 2017). "Spinal muscular atrophy is due to mutations affecting the SMN1 gene coding for the full-length protein (survival motor neuron; SMN) and the SMN2 gene that preferentially generates an exon 7-deleted protein (SMNΔ7) by alternative splicing." (PMID 29292768, 2017). "Several potent molecules correcting the splicing deficit of the SMN2 (survival of motor neuron 2) gene have been identified and these molecules are moving towards a potential therapy for spinal muscular atrophy (SMA)." (PMID 29133793, 2017). "For example, most SSOs systematically covering SMN2 exon 7 stimulated exon skipping, which is required for antisense therapy of spinal muscular atrophy, however, ~20% increased exon inclusion." (PMID 26732650, 2016).
spinal muscular atrophy (continued). "Both survival of motor neuron (SMN) genes are associated with spinal muscular atrophy; mutations in SMN1 cause the disease, and SMN2 modulates its severity." (PMID 27917293, 2016). "Spinal muscular atrophy (SMA) is caused by SMN1 dysfunction, and the copy number of SMN2 and NAIP can modify the phenotype of SMA." (PMID 25888055, 2015). "Trichostatin A (TSA) is a histone deacetylase inhibitor with beneficial effects in spinal muscular atrophy mouse models that carry the human SMN2 transgene." (PMID 24984019, 2014). "VPA is currently being tested for the treatment of additional diseases, such as spinal muscular atrophy, where it promotes inclusion of a critical alternative exon into the SMN2 pre-mRNA." (PMID 24358235, 2013). "VPA is in clinical tests to treat spinal muscular atrophy, as it promotes inclusion of exon 7 of the SMN2 gene." (PMID 24358235, 2013). "TOES have been first tested for their ability to induce the inclusion of SMN2 exon 7 in spinal muscular atrophy (SMA) patient fibroblasts." (PMID 24285959, 2013). "Two almost identical SMN genes are present on chromosome 5q13: the telomeric or SMN1 gene, which is the spinal muscular atrophy- determining gene, and the centromeric or SMN2 gene." (PMID 22047105, 2011). "TSA increased SMN2 gene expression in a mouse model of spinal muscular atrophy (SMA), and significantly enhanced exon 7 inclusion (the splicing defect) in SMN2 transcripts." (PMID 20020055, 2009). "The spinal muscular atrophy (SMA) phenotype strongly correlates with the SMN2 gene copy number." (PMID 39463208, 2024). "Finally, the phase III SPR1NT trial (NCT03505099) evaluated the efficacy and safety of onasemnogene abeparvovec in presymptomatic infants with spinal muscular atrophy (SMA) type 1 who have two copies of the SMN2 gene." (PMID 39202360, 2024). "When applied to SMN2, a therapeutic target for spinal muscular atrophy, SpliceRUSH robustly identifies not only known SREs but also a previously unknown distal intronic SRE, which can be targeted to alter exon 7 splicing using either dCas13d/gRNA or ASOs." (PMID 38714659, 2024). "Building on the encouraging results of treating spinal muscular atrophy by modifying aberrant splicing in the SMN2 gene, it may also possible to develop small molecular drug for the hemophilic mutations that cause aberrant splicing." (PMID 35269902, 2022). "Spinal muscular atrophy (SMA) is the first human disease for which an antisense oligonucleotide (ASO)-based therapy based on the successful prevention of skipping of an exon (SMN2 exon 7) became available." (PMID 34445083, 2021). "Indeed, hnRNP A1 has been linked to the exclusion of exon 7 within survival motor neuron (SMN2), a key aetiological event of the neurodegenerative disease spinal muscular atrophy (SMA)." (PMID 32748079, 2020). "Finally, we demonstrate the activation of SMN2 exon 7 splicing in spinal muscular atrophy (SMA) patient fibroblasts, suggesting a potential application of the CASFx system." (PMID 32532987, 2020). "An illustrative example of a vastly complex and cooperative RNA structural arrangement which governs AS is present within survival motor neuron 2 (SMN2) transcript which is critical for development of spinal muscular atrophy (SMA), a genetic disease fatal at early age." (PMID 32708277, 2020). "For example, in spinal muscular atrophy, causative loss-of-function mutations in SMN1 can be rescued by a recently approved therapy which uses an antisense compound to promote exon retention in an alternatively spliced yet otherwise identical paralog, SMN2." (PMID 30216339, 2018). "Indeed, recent studies identified compounds with therapeutic potential for the treatment of spinal muscular atrophy that selectively influence SMN2 AS and perhaps a small number of other targets." (PMID 29235465, 2017).
spinal muscular atrophy (continued). "Spinal muscular atrophy represents an incredibly suitable target for the use of ASOs because of the presence of the defective SMN2 rescue gene, the duality of both weak 3′ and 5′ exon 7 splice-sites and the presence of many local and regional splicing silencers and enhancers." (PMID 24400925, 2014). "For example, we have mined the Johnson and Johnson and Connectivity Map databases for agents that modulate SMN2 mRNA levels, the rescuing paralog for spinal muscular atrophy (SMA; OMIM [253300]), rapidly identifying a role for p38 kinase in the modulation of SMN levels." (PMID 22704758, 2012). "Spinal Muscular Atrophy (SMA), a severe autosomal recessive genetic disease in infants characterized by motor impairment and premature lethality, caused by mutations or loss of SMN1 and retention of SMN2." (PMID 22022549, 2011). "Spinal muscular atrophy (SMA) is caused by low survival motor neuron (SMN) levels and patients represent a clinical spectrum due primarily to varying copies of the survival motor neuron-2 (SMN2) gene." (PMID 21249120, 2010). "The motor neuron (MN) disease spinal muscular atrophy (SMA) is caused by recessive mutations of the survival motor neuron 1 (SMN1) gene, retention of variable copies of an alternatively spliced, paralogous gene SMN2, and deficient expression of the SMN protein." (PMID 36997967, 2023). "Consequently, many AS-mediated diseases associated with nervous tissues are reported, including spinal muscular atrophy (SMA), resulting from Smn2 missplicing; autism spectral disorder (ASD), determined by a low expression of nSR100 (Srrm4) splicing factor; and many others." (PMID 36980872, 2023). "Spinal muscular atrophy is an autosomal recessive neurological disorder in children that is caused by homozygous loss of the survival motor neuron 1 (SMN1) gene with the retention of the hypomorphic SMN2 gene leading to reduced levels of the ubiquitously expressed SMN protein." (PMID 36419936, 2022). "The proof of concept is the FDA-approved treatment for spinal muscular atrophy (SMA) where the drug Spinraza® modifies the existing SMN2 gene through the intrathecal administration of four loading doses of oligonucleotides in such a way that the SMN2 gene is produced in higher amounts." (PMID 36366382, 2022). "For example, nusinersen—a phosphorothioate (PS) ASO with 2′-O-methoxyethyl (2′-O-MOE) modifications—was designed to induce exon 7 inclusion in SMN2 and received FDA approval for the treatment of spinal muscular atrophy." (PMID 41036464, 2025). "We found reduced expression of SMN2 due to SMN1 conversion, potentially affecting spinal muscular atrophy, and increased expression of translocated duplications of AMY2B." (PMID 39149335, 2025). "It is a pharmaceutical agent designed to manage spinal muscular atrophy (SMA), serving as a modifier of survival motor neuron 2 (SMN2)-directed RNA splicing." (PMID 40733277, 2025). "We recruited 17 subjects with type II or type IIIa spinal muscular atrophy (SMA)and obtained the SMN1 and SMN2 copy numbers in 16 of them." (PMID 38230872, 2024). "We present the case of a female patient with spinal muscular atrophy (SMA) and three survival motor neuron 2 (SMN2) gene copies." (PMID 38306058, 2024). "In the spinal muscular atrophy (SMA) mouse model, NOVA1 expression and survival of motor neuron 2 (SMN2) were synchronously downregulated." (PMID 37887320, 2023). "Because spinal muscular atrophy is a very rare disease, we had a highly heterogenous group in terms of SMA type, SMN2 copy number and age." (PMID 36551943, 2022). "Nusinersen, an ASO approved by both FDA and EMA, increases inclusion of exon 7 in SMN2 transcript, thus resulting in increases in SMN proteins, which have therapeutic effects for all types of spinal muscular atrophy." (PMID 34591693, 2022).
spinal muscular atrophy (continued). "These drugs are ideal in terms of delivery as they can be taken orally, and positive results have been observed in rodent models of spinal muscular atrophy (SMA) that were treated with small molecules that target and degrade SMN2 RNA." (PMID 34211373, 2021). "Other notable genes include SMN1 (94.6% dark CDS) and SMN2 (88.0% dark CDS), which are known to be involved in spinal muscular atrophy (SMA) and ALS." (PMID 31104630, 2019). "Recently, we have shown that reduced NCALD levels protect against spinal muscular atrophy (SMA) in individuals carrying homozygous deletion of SMN1 and only four SMN2 copies." (PMID 30853885, 2019). "SMN protein is expressed from two genes, SMN1 and SMN2, but the SMN1 gene is homozygously disrupted in people with spinal muscular atrophy; as a consequence, all of the SMN that is expressed in people with this disease is from the SMN2 gene." (PMID 28728573, 2017). "Proximal spinal muscular atrophy (SMA) is a neuromuscular disorder caused by the degeneration of alpha motor neurons and is characterized by a mutation in the survival motor neuron gene (SMN1); however, all patients retain a nearly identical copy of SMN2." (PMID 29104258, 2017). "We have investigated the molecular mechanism and activity of these molecules in spinal muscular atrophy (SMA), a genetic neuromuscular disease where a silent exonic transition on the survival motor neuron 2 (SMN2) leads to exon 7 (E7) skipping." (PMID 25557785, 2015). "CNV detection in genes such as PMS2 (Lynch syndrome) and SMN1 (Spinal Muscular Atrophy) is notoriously challenging because of high-similarity paralogs (PMS2CL and SMN2) that cause nonspecific read alignment and distorted read depth." (PMID 41595524, 2026). "Their potential has been demonstrated by the United States Food and Drug Administration’s (FDA) approval of risdiplam for the treatment of spinal muscular atrophy (SMA), where it promotes the inclusion of exon 7 in SMN2, whose product then compensates for SMN1-inactivating mutations." (PMID 38609352, 2024). "Aiming to develop a treatment for spinal muscular atrophy (SMA), they investigated if the Na+/H+ channel inhibitor 5-(N-ethyl-N-isopropyl)-amiloride (EIPA) could promote exon 7 inclusion in the SMN2 mRNA." (PMID 34065983, 2021). "Spinal muscular atrophy (SMA) is currently classified into five different subtypes, from the most severe (type 0) to the mildest (type 4) depending on age at onset, best motor function achieved, and copy number of the SMN2 gene." (PMID 32751151, 2020). "Several studies have demonstrated that phosphorothioate and 2′-O-methoxyethyl- modified ASOs targeting the splicing cis element called ISS-N1 increase SMN2 exon 7 inclusion, thus increasing levels of SMN protein, alleviating the symptoms in patients with spinal muscular atrophy." (PMID 29439487, 2018). "In people with the disease spinal muscular atrophy (SMA), both alleles of SMN1 are non-functional, but increased levels of SMNFL, usually resulting from SMN2 gene duplication, correlate with longer survival times." (PMID 28728573, 2017). "In the neurodegenerative disorder spinal muscular atrophy (SMA), Sam68 has been shown to be a novel and crucial regulator of SMN2 alternative splicing, acting as a splicing repressor of exon 7 inclusion through both its cooperation with hnRNP A1 and its RNA binding ability." (PMID 24287914, 2013). "For example, VPA was found to trigger DNA demethylation and restore the splicing pattern of SMN2 transcripts in fibroblast cultures derived from proximal spinal muscular atrophy (SMA) patients via Htra2-β1, the splicing factor essential for the inclusion of exon 7 into SMN2 mRNA." (PMID 22200904, 2012).
spinal muscular atrophy (continued). "Here we report the development of a complete genetic model of spinal muscular atrophy (SMA) in the vertebrate zebrafish to complement existing zebrafish, mouse, and invertebrate models and show its utility for testing compounds that alter SMN2 splicing." (PMID 21443782, 2011). "Nusinersen is used in the treatment of spinal muscular atrophy and induces inclusion of SMN2 Exon 7 through steric blocking of an intronic splicing silencer downstream of the exon, leading to increased production of full-length and functional SMN protein from SMN2." (PMID 39471777, 2024). "Spinal muscular atrophy (SMA) is a neuromuscular disorder arising from biallelic non-functional survival motor neuron 1 (SMN1) genes with variable copies of partially functional SMN2 gene." (PMID 36911944, 2023). "Spinal muscular atrophy (SMA) as a prototype is an excellent example, where, the majority of SMA patients are homozygous for SMN1-exons 7-8 deletion; however, phenotype severity is directly influenced by SMN2 (SMN1 pseudogene) copies that determine SMA subtype and can ameliorate the SMA phenotype." (PMID 37628591, 2023). "However, a higher-order multiplexing dPCR assay for measuring SMN1 and SMN2 copy numbers in spinal muscular atrophy (SMA) samples has not been reported." (PMID 33199817, 2020). "The outlook for children affected with spinal muscular atrophy, a childhood motor neuron disorder which in its most severe form is uniformly lethal in infancy, has been transformed by the advent of nusinersen, an ASO which alters the splicing of the SMN2 gene to produce more full length SMN protein." (PMID 30054789, 2018). "Indeed, NBS for spinal muscular atrophy is nowadays largely accepted amongst pediatricians, families and advocacy groups, although screening assays specifically focus only on the identification of homozygotic deletions of the SMN1 gene and miss SMN1 heterozygotic and SMN2 deletions." (PMID 33542429, 2021). "Two independent studies used a high-throughput, cell-based screen to identify compounds that promote the inclusion of a skipped exon in SMN2 pre-mRNA, thus restoring the expression of the SMN protein that is lacking in patients with spinal muscular atrophy." (PMID 36413497, 2022). "Notably, genetic evaluation excluded a differential diagnosis of alternate conditions, including spinal muscular atrophy (SMA), through negative SMN1/SMN2 deletion/duplication analysis, and Pelizaeus-Merzbacher disease, as PLP1 mutation analysis was negative." (PMID 40243727, 2025).